KIT (KIT proto-oncogene, receptor tyrosine kinase)
Diseases named in the same sentence as KIT in open-access papers (continued):
Sharing a sentence is not in itself a finding about the gene and the disease.
tumor (continued). "The results showed that the inhibition of c-KIT and HSP90β by radotinib led to a profound suppression of tumor growth, as evidenced by a significant reduction in tumor volume and weight." (PMID 29127384, 2017). "CHMFL-KIT-031 showed potent inhibitory efficacy for KIT V559D mediated signaling pathways in cell and anti-tumor activity in vivo (Tumor Growth Inhibition: 68.5%)." (PMID 29340041, 2017). "In a recent study of a cohort of 75 tumours from patients with a mucosal melanoma, NF1 and RAS mutations were identified in 18.3 and 16.9% samples, respectively, whereas 8.4 and 7% of tumour samples harboured BRAF and KIT mutations." (PMID 28637487, 2017). "We have confirmed that radotinib inhibits c-KIT-positive AML cell lines using HEL92.1.7 cells in the xenograft tumor mouse model." (PMID 29127384, 2017). "Potent KIT inhibitors such as dasatinib and pazopanib also cause ALT and AST elevations in about 50% of tumor patients, and hepatocellular necrosis has been shown in patients treated with pazopanib." (PMID 28716061, 2017). "KIT positivity is a major defining feature for the diagnosis of GIST for a tumor that has morphological features compatible with GIST, although KIT positivity alone is not sufficient for the diagnosis." (PMID 26276366, 2016). "A previous report investigating clonality in familial GIST patients with germline KIT mutations indicated that cells in the ICC hyperplasia have polyclonal proliferation, whereas GIST tumor cells show a monoclonal development." (PMID 26511941, 2016). "The histochemical staining of p55PIK and KIT proteins in tumor samples was quantitatively determined and showed that the expression of both p55PIK and KIT were strongly increased in IMA-resistance tumor samples." (PMID 26587973, 2016). "c-KIT is dysregulated in many diseases, including cancer; in neoplastic diseases, its increased expression and auto-phosphorylation allows tumor cells to develop independently from growth and survival signals." (PMID 26942875, 2016). "The tumor stained positively for CD117 (KIT) and CD34, and it was composed of spindle cells with >5 mitoses/50 high-power fields (HPF)." (PMID 27864817, 2016). "A compromise has been adopted by employing half-dose imatinib in a KIT exon-11 germline mutant with multiple GISTs, obtaining marked tumor reductions after one-year." (PMID 27437068, 2016). "Afatinib resistant tumor cell killing by [ERBB3 + c-KIT + c-MET] knock down was significantly, though only partially i.e. ∼70% reduction, reduced by knock down of eIF2α, CD95 or Beclin1 (p < 0.05)." (PMID 26934000, 2016). "The tumor stained positively for CD117 (KIT) and was composed of spindle cells with 19 mitoses/50 HPF." (PMID 27864817, 2016). "Significantly, over-expression of p55PIK and KIT was observed in all IMA-resistance samples (a patient tumor sample, pre- and post-treatment)." (PMID 26587973, 2016). "Imatinib is an inhibitor of tyrosine kinases including KIT, and targets the aberrant signaling pathways that are critical for tumor cell proliferation and survival, thus showing anti-tumor activity." (PMID 26957123, 2016). "The tumour from patient #2 presented variable 5–10 fold amplification across 4q12, which included the tyrosine kinase KIT, and tyrosine kinase receptors PDGFRA and KDR (VEGFR2)." (PMID 27843499, 2016). "Selectively, in afatinib resistant clones, combined knock down of ERBB3, c-KIT and c-MET caused tumor cell death." (PMID 26934000, 2016). "By contrast, tumor size in Group A patients was greater (10.1 ± 5.8 cm) than in Group B (4.7 ± 1.9 cm; p = 0.0002), whereas the frequency of the WT status for both KIT and PDGFRA was lower in Group A than B (14.3 % vs. 50 %; p = 0.009)." (PMID 26867653, 2016).
tumor (continued). "Pathological examination revealed that the tumor was composed of viable spindle cells with 15 mitoses/50 HPF that stained positively for CD117 (KIT) and CD34." (PMID 27864817, 2016). "Altogether, 151 up- and 64 down-regulated genes were identified between UVB-irradiated and non-irradiated skin biopsies, among which down-regulated DNAJB4 and SLIT2 were annotated as tumor-suppressors and up-regulated KIT was annotated as an oncogene." (PMID 27829444, 2016). "In contrast to MCTs, no mutation was found in these two exons (11 and 17) of c-kit gene in KIT-positive neoplasms of vascular cell origin." (PMID 27422008, 2016). "Canine HSA cell lines and tumor samples have been shown to express the receptor tyrosine kinases stem cell factor receptor (KIT), platelet derived growth factor receptor (PDGFR) and vascular endothelial growth factor receptor (VEGFR) family members." (PMID 26062540, 2015). "Dramatic metabolic responses following imatinib treatment indicate a high, KIT-dependent glucose turnover which has been particularly helpful for predicting tumor response to imatinib." (PMID 25781619, 2015). "Significant tumor regression upon imatinib treatment in a c-KIT-overexpressing HGESS case supports further use in the clinic." (PMID 26576131, 2015). "The confirmed presence of disease-driving, activating mutations in KIT or PDGFRα in GIST can today, e.g., be used to predict tumor recurrence and identify patients who are likely to benefit from adjuvant therapy." (PMID 26583076, 2015). "We showed that knocking down the receptors for Prokineticin provides a more effective way to inhibit the tumor formation than directly targeting c-KIT, by abolishing the de novo generation of c-KIThigh cells." (PMID 26682270, 2015). "ZNF671 re-expression in UC cell lines, via ectopic expression, inhibited tumor growth and invasion, in possible conjunction with downregulation of cancer stem cell markers (c-KIT, NANOG, OCT4)." (PMID 26320192, 2015). "Multiple receptor tyrosine kinases are known to be expressed by HSA tumor cells including KIT, PDGFR, and VEGFR, although their contributions to tumor growth are not clear." (PMID 26062540, 2015). "Regarding localization of the primary tumor, those cases with mutation in exon 11 of the c-KIT gene showed the same distribution as for GIST as a whole, that is, almost 60% of neoplasm in the stomach and 40% in the small intestine." (PMID 25885906, 2015). "These include mutations in several protein kinase genes including KIT, PDGFRα, and BRAF that are known to regulate fundamental processes in oncogenesis including tumor proliferation, metastasis, neo-vascularization, and chemo-resistance." (PMID 24507750, 2014). "Studies indicate that approximately 95% of the cases are KIT positive which confers the tumor with proliferative potential as well as the ability to evade apoptotic pathways." (PMID 25185706, 2014). "Immunohistochemical analysis of the tumor cells revealed focal positivity for c-KIT and SMA, and negativity for CD34 and S-100." (PMID 25037940, 2014). "A third resection was realized and a histopathological examination showed the same AF tumor with a low positivity of c-KIT." (PMID 25488584, 2014). "Studies with MCC cell lines show that KIT is activated by paracrine or autocrine tumor cell-derived SCF which stimulates growth of MCC in vitro." (PMID 24634783, 2014).
tumor (continued). "Taken together, the combination of a HSP90AA1 inhibitor and a MTOR inhibitor not only activates autophagy, leading to KIT downregulation, but also likely exerts anti-angiogenic effects that to contribute to tumor growth inhibition in vivo in our study." (PMID 25375091, 2014). "Only 1 mixed intratubular SEM/LCT tumor from the biopsy group showed simultaneous co-expression of c-KIT and PLAP." (PMID 25096628, 2014). "The neoplasm metastasis associated genes KRT20, tumor protein D52 (TPD52), MUC1, and KIT are upregulated in the poor prognosis tumors while homeobox B1 (HOXB1) is downregulated." (PMID 24634783, 2014). "Activating mutations in and/or gene copy number increases of a receptor tyrosine kinase KIT, found in 39% of mucosal and 36% of acral melanoma, are a plausible cause of the ERK pathway activation in these tumour cells." (PMID 25413220, 2014). "Pathway analysis suggested that potentially actionable mutations in wild-type tumours, including NF1, KIT and NOTCH1, were spread over various signalling pathways." (PMID 24752294, 2014). "The tumor probably arises from KIT or platelet-derived growth factor receptor A (PDGFRA) gene mutations in precursor cells that normally give rise to the interstitial cells of Cajal." (PMID 24587795, 2014). "Most mutations are somatic (in tumor tissue only), however, patients with familial GIST syndrome have constitutional KIT/PDGFRA mutations; greater than 10 families have been reported worldwide with mutations generally similar to those in sporadic GISTs." (PMID 25264210, 2014). "Regorafenib is a multikinase inhibitor that blocks targets and receptors including VEGFR1–3, TIE2, PDGFR, FGFR, KIT, and RET, which are associated with angiogenesis and tumor progression." (PMID 24587795, 2014). "In mice with established GIST xenografts, treatment with either 1st or 2nd gen human anti-KIT dTc led to significant reductions in tumor growth rates." (PMID 23433424, 2013). "The present report demonstrates encouraging initial results for anti-KIT dTc and provides the rationale for further pre-clinical testing of this novel immunotherapeutic anti-tumor agent." (PMID 23433424, 2013). "Further investigation into the c-KIT gene will determine the role of imatinib mesylate therapy in these tumours." (PMID 23841010, 2013). "Sunitinib is a multitarget TKI against vascular endothelial growth factor receptor (VEGFR), platelet-derived growth factor receptor (PDGFR), and c-KIT that is effective in eliciting tumor response and disease stabilization in imatinib-resistant GISTs." (PMID 23983708, 2013). "Cases with both PDGFRA and KIT amplification had a younger age of diagnosis (median = 53.7 yrs) compared with other amplified tumours (median = 60.3 yrs, p = 0.046, t test)." (PMID 23990986, 2013). "In that case report, a 46-year-old male patient with KIT-positive GIST of the ascending colon underwent postoperative imatinib therapy because the circumferential tumor margins were histologically positive." (PMID 23606918, 2013). "As for the other three possible tumor subtypes, ALDH2 was associated with KIT exon 11 insertions (p = 0.03) and the null GSTT1 genotype was associated with PDGFRA-mutated tumors (p = 0.04)." (PMID 23637977, 2013). "To determine the ability of anti-KIT dTc to traffic to, infiltrate, and limit growth of established tumor, we utilized a subcutaneous xenograft model." (PMID 23433424, 2013). "Taken together, our initial study of anti-KIT dTc supports their further development as a novel treatment for KIT+ neoplasms, including those which have developed clinical resistance to kinase-inhibitor therapy." (PMID 23433424, 2013). "Specifically, Imatinib mesylate targets PDGF receptors while KIT was indicated as a mediator of anti-tumor activity in patients with recurrent GBM." (PMID 23537212, 2013). "As a result of the introduction of anti-KIT tyrosine kinase inhibitors in their treatment, these tumours have become better known." (PMID 23634309, 2013).
tumor (continued). "Using an alternative strategy, we engineered a CIR that contains the natural ligand for KIT, which allows for recognition of KIT+ tumor cells." (PMID 23433424, 2013). "In the twelve KSs of the skin, the c-KIT positivity was correlated to the pathological stage of the tumor." (PMID 23936513, 2013). "1st and 2nd gen dTc were produced and tested in vitro and in vivo to demonstrate their efficacy in destroying KIT+ tumor cells." (PMID 23433424, 2013). "KIT expression was often restricted to isolated tumour cells, whilst VEGFR2 frequently gave a granulated cytoplasmic staining in addition to decoration of the cell membranes." (PMID 23990986, 2013). "Finally, it may be argued that further molecular characterization, for example, the identification of specific KIT mutations that affect various gene domains, may be significant in the selection of tumour subgroups and the prediction of their clinical outcome and response to selective therapy." (PMID 23833657, 2013). "IFNγ production confirmed dTc activation by KIT+ tumor and was found to be in the range of 462-475 pg/ml, while production by CIR- T cells was negligible (p<0.001)." (PMID 23433424, 2013). "Having demonstrated that the anti-KIT dTc were stimulated to divide in vitro in response to KIT+ tumor and lyse KIT+ targets, we sought to measure the in vivo efficacy." (PMID 23433424, 2013). "We demonstrated that 2nd gen dTc effectively lysed KIT+ tumor and were more effective than the 1st gen format by LDH release." (PMID 23433424, 2013). "In vitro dTc proliferation and tumoricidal capacity in the presence of KIT+ tumor cells were measured." (PMID 23433424, 2013). "Significant delays in tumor growth following a single dTc infusion in our in vivo model support the potential utility of anti-KIT dTc for the treatment of GIST." (PMID 23433424, 2013). "In those 17 tumors, the signal for KIT, which has a molecular weight of 145 kDa, was also confirmed in the tumor tissues." (PMID 23420128, 2013). "Both CD105 and c-KIT rate of the spindle-shaped tumor cell positivity increased in parallel to the pathological stage." (PMID 23936513, 2013). "The KL component is expressed on the extracellular aspect of the CIR to enable interaction with KIT on the surface of target tumor cells." (PMID 23433424, 2013). "Using a xenograft model, we demonstrated that systemic infusions of 1st and 2nd gen anti-KIT dTc resulted in significant reductions in tumor growth rates." (PMID 23433424, 2013). "Positive immunohistochemical staining for CD117 is also a defining feature of EGISTs, and it correlates with a tumor response to treatment with the KIT kinase activity inhibitor." (PMID 23420829, 2013). "Our histologic studies confirmed that anti-KIT dTc traffic to KIT+ tumors and mediate tumor necrosis after intravenous infusion." (PMID 23433424, 2013). "Use of additional grade III tumor samples for KIT expression analyses would fully resolve this issue." (PMID 22672386, 2012). "Positive immunoreactivity for KIT in the cytoplasm of tumor cells was noted in 8/24 primary and 3/10 metastatic AGASACA and 9/15 TC samples." (PMID 22630170, 2012). "Continued work in this area would help elucidate the relative contribution of deranged KIT expression to the oncogenic pathways operative in this neoplasia, thus facilitating optimization of treatment modalities." (PMID 22672386, 2012). "A clonal KIT amplicon was present in aneuploid populations sorted from the primary tumor and in divergent subclones arising in metastatic foci found in the brain, lung, and jejunum." (PMID 23029135, 2012). "All the other cases, except the one discussed here showed normal KIT copies in the tumor tissues and their constitutional counterparts." (PMID 22672386, 2012). "Our results provide a unique description of the clonal evolution of aneuploid tumor populations with a common c-KIT amplicon during the progression to metastatic MSC." (PMID 23029135, 2012).
tumor (continued). "c-KIT positive tumour cells were revealed in 32/44 (73%) examined sections, which is in discrepancy with the role of this protein as a marker for human SE." (PMID 22986090, 2012). "Patient with NRAS, KIT, and GNAQ mutations were also enrolled on specific trials directed at their tumor mutation status." (PMID 22536370, 2012). "Immunohistochemically, the tumor cells showed weak and diffuse positivity for KIT, which exhibited a combination of cytoplasmic and membranous patterns, and gastric GIST of mixed spindle-epithelioid cell types was diagnosed." (PMID 23227375, 2012). "We detected several aberrations, including amplification of a region on chromosome 4q, which includes KIT, in all four flow sorted tumor specimens." (PMID 23029135, 2012). "In primary KIT+ tumor cultures, nucleated tumor cells expanded in the absence (4.6±0.4-fold), but not the presence (1.2±0.5-fold) of imatinib (p = 0.01)." (PMID 23285214, 2012). "In both of these cases the tumour cells contained PAS positive cytoplasmic granules and in one case, the PLAP+/PAS + tumour cells also stained strongly for c-KIT." (PMID 22986090, 2012). "In most tumors, progressive decrease in c-KIT expression is reported as long as the tumor grows and invades, being positive in normal tissues and decreased in tumor cells." (PMID 22839358, 2012). "Although there are a significant number of other tumor types which express c-KIT, there remains controversy as to its relationship to patient outcome." (PMID 22839358, 2012). "In the other case, only a few of the PLAP + tumour cells were c-KIT positive, and this tissue was also morphologically consistent with SS." (PMID 22986090, 2012). "A small number of genes are recurrently mutated in TGCT, including KIT, KRAS2 and BRAF, but in each case these represent <10% of tumours analysed." (PMID 23068969, 2012). "In clinical trials of patients with GIST, treatment with either sunitinib (both at 50 mg/day on Schedule 4/2 and at 37.5 mg on the CDD schedule) or imatinib was found to be highly efficacious, suggesting that KIT inhibition was critical for tumor control." (PMID 22897944, 2012). "Taken together all these results paint a somewhat diverse picture of the expression of c-KIT in germinal tumours." (PMID 22986090, 2012). "Inhibitors of the KIT tyrosine kinase have recently been introduced and successfully applied as a therapeutic agent for this tumour type." (PMID 22747577, 2012). "BRAF-wild-type clones present in primary tumours and metastases are likely to contain mutations or copy number alterations affecting genes other than BRAF, such as NRAS, KIT, cyclin D1, PTEN and CDKN2A." (PMID 21224857, 2011). "Biomarker analyses of HCC patients treated with sunitinib showed a correlation between decreased levels of IL-6 and soluble c-KIT and a delayed tumor progression; vice versa elevated levels of IL-6 and c-KIT were associated with an unfavorable disease course." (PMID 22072937, 2011). "Somatic mutations in these genes have also been described in sporadic tumours and in the case of GIST, activating mutations in KIT are predictors of response to targeted therapy with imatinib." (PMID 21575252, 2011). "Tumor specimen showed wild-type genotype for exons 9, 11, 13, 17 of the KIT or exons 12, 14 and 18 of PDGFRA genes." (PMID 20684773, 2010). "Needle biopsy was performed and the results showed spindle shaped tumor cells that were positive for c-KIT." (PMID 20718969, 2010). "Tumor endothelial cell KIT expression was strongly (P < 0.01) associated with endothelial cell phospho‐KIT and SCF expression, and with tumor KIT (P = 0.0011) and VEGFR‐2 expression (P = 0.022)." (PMID 20030644, 2010). "Results on the use of imatinib (Gleevec), a KI with high activity against KIT and PDGFR, have been disappointing with responses possibly correlated with either KIT mutation or high-level KIT protein expression (e.g. ≥75% of tumor cells)." (PMID 19949544, 2009).